CX3CL1 (C-X3-C motif chemokine ligand 1)
Diseases named in the same sentence as CX3CL1 in open-access papers (continued):
Sharing a sentence is not in itself a finding about the gene and the disease.
tumor (continued). "Specific enhanced recruitment of CX3CR1-T cells towards CX3CL1-expressing tumor cells was observed, which lead to reduced tumor growth." (PMID 27096098, 2016). "This study demonstrates that ectopic expression of CX3CR1 enhanced the homing of adoptively transferred T cells towards CX3CL1-producing tumors, resulting in increased T cell infiltration in tumor tissues and decreased tumor growth." (PMID 27096098, 2016). "Assessment of REMBRANDT data also revealed that CX3CL1 mean expression intensity was decreased in human GBM samples compared to non-tumor control samples." (PMID 25987130, 2015). "On the other hand, CX3CL1 plays a pivotal role in tumor angiogenesis, as well as in adhesion and migration of cancer cells, reinforcing their ability to spread and metastasize." (PMID 24799766, 2014). "On the one hand, CX3CL1 stimulates a strong immune response with the recruitment of NK cells and tumor-specific T cells." (PMID 24799766, 2014). "Another chemokine GPCR, CX3CR1, and its ligand, CX3CL1, recruit TAMs and sustain the survival of TAMs to promote tumor metastasis." (PMID 25110692, 2014). "Normal and malignant breast tissues express CX3CR1 but its overexpression increases the ability of tumor cells to migrate to skeleton and brain where bone stromal cells and neurons release soluble CX3CL1." (PMID 24799766, 2014). "TILs express additional chemokine receptor, CX3CR1, and the expression of its ligand, CX3CL1, is elevated in tumor cells in colorectal cancer tissues." (PMID 24966464, 2014). "Tumor cells from PDAC patients strongly expressed CX3CR1 that mediates migration to CX3CL1 constitutively expressed by neural cells." (PMID 24799766, 2014). "The induction of cell to cell contact by CX3CL1 prevented detachment of tumor cells from the tumor aggregate that is required for the invasion process." (PMID 24799766, 2014). "ADAM17 is involved in the cleavage of numerous surface molecules, most of which are considered to be relevant in tumour-associated processes such as cell growth, migration and invasion (TNF-α, CD44, L1-CAM, L-selectin, ICAM1, CX3CL1, etc.)." (PMID 25246708, 2014). "Compared to primary tumor cells, BM-infiltrating NB cells down-modulated the expression of CX3CL1, AGT, ATP1A2 mRNAs, whereas they up-regulated several genes commonly expressed by various lineages of BM resident cells." (PMID 22253825, 2012). "While CX3CL1 is a known target of FGF signaling in the wound healing environment, these studies demonstrate that FGFR activation also leads to induction of CX3CL1 in a tumor setting." (PMID 23029290, 2012). "In this paper we have shown for the first time that iFGFR1-induced CX3CL1 regulates the migration of macrophages during the initial stages tumor formation." (PMID 23029290, 2012). "The intensity of CX3CL1 staining and the fraction of tumor cells stained for CX3CL1 were variable in our cohort of 54 patients with advanced primary EOC." (PMID 21750716, 2011). "In these tumors, it was detected mostly in malignant cells, making tumor cells the most significant source of CX3CL1 in EOC." (PMID 21750716, 2011). "In serous and mucinous benign and borderline tumors, CX3CL1 immunoreactivity was detected in proliferating tumor cells derived from the epithelium." (PMID 21750716, 2011). "Chemokines such as CXCL10 and CX3CL1 can attract NK cells that can directly kill tumor cells." (PMID 40145607, 2025). "At the same time, CX3CL1 enhances the secretion of immunosuppressive factors, inhibits the anti-tumor activity of effector T cells and NK cells, and promotes immune escape and tumor growth." (PMID 41376630, 2025). "It was speculated in another Mendelian randomization study that CX3CR1 on CD14+ CD16- monocytes may promote the onset of PC through the CX3CR1/CX3CL1 signaling pathway, which is actively involved in promoting tumor angiogenesis, migration, and infiltration." (PMID 40564200, 2025).
tumor (continued). "Moreover, the nuclear translocation of p65/p50 enhanced the transcription of CCL5 and CX3CL1, prompting tumor cells to release more T cell chemokines." (PMID 40995667, 2025). "Notably, CAR-M post-tumor stimulation exhibited elevated secretion of T/NK cell-recruiting chemokines (Cx3cl1, Ccl5, Cxcl10), with Cxcl10 secretion further validated by ELISA." (PMID 41388305, 2025). "In the field of cancer immunotherapy, CAR-T cells engineered to co-express CX3CR1 (NKG2D-CX3CR1 CAR-T) have been shown to enhance tumor infiltration and antitumor efficacy, demonstrating robust therapeutic effects, especially in tumor models with high CX3CL1 expression." (PMID 40508161, 2025). "CX3CL1 protein levels were also elevated in tumor lysates at ZT2 compared to ZT18." (PMID 41279119, 2025). "Furthermore, CX3CL1 expressed by DCs promotes tumor infiltration of CD4+ and CD8+ T cells, correlating with improved prognosis." (PMID 41445742, 2025). "The induction of CX3CL1 could therefore modulate the tumour-suppressive activity of PARP inhibitors in certain patients." (PMID 39862711, 2025). "Finally, in contrast to the results in the intraperitoneal model, Cx3cl1 led to a significantly reduced tumour growth in the primary tumour model." (PMID 39862711, 2025). "Moreover, they facilitate metastasis by carrying molecules like CX3CL1, which prepare distant organs for tumor invasion through chemokine and cytokine network modulation." (PMID 40103824, 2025). "Finally, we co‐cultured CD4+ T cells with tumor cells for 48 h and found that the exogenous addition of CX3CL1 significantly promoted the secretion of IL10 and TGFβ." (PMID 39783838, 2025). "We therefore hypothesise that tumour cell-tumour cell or tumour cell-mesothelial cell interactions through the CX3CL1/CX3CR1 system may be responsible for the tumour-promoting effect." (PMID 39862711, 2025). "Among them, the chemokine family, including CC (e.g., CCL1, CCL3, CCL5, CCL7, and CCL15), CXC (e.g., CXCL1, CXCL3, CXCL5, and CXCL10), XC (e.g., XCL1 and XCL2), and CX3C (e.g., CX3CL1), plays a pivotal role in tumor development, metastasis, and chemotherapy resistance 30-33." (PMID 40740234, 2025). "Thus, the IL-15Rc-HIF-1α-CX3CL1 signaling pathway links tumor cells with macrophages in the breast TME." (PMID 39858015, 2025). "CX3CL1 was expressed in squamous neoplastic lung tissues at all grades of tumor differentiation." (PMID 41210693, 2025). "In addition, the expression of CX3CL1, a T-cell-associated chemokine, was increased along with CCL8 in the tumor microcirculation after cabozantinib treatment." (PMID 40508161, 2025). "For example, HCC-derived CX3CL1 facilitates tumor infiltration and induces apoptosis." (PMID 40051011, 2025). "However, no increased CX3CL1 concentration was detectable in ascites of mice with Cx3cl1+ tumours (0.08 vs. 0.10 ng/mg, P = 0.72)." (PMID 39862711, 2025). "As we found CX3CR1 expression in the tumour cells of the mouse model as well as high levels of CX3CL1 in peritoneal metastases of the HGSOC cohort, we agree that the receptor may play an important role for the overall negative outcome in survival." (PMID 39862711, 2025). "Furthermore, we established that CX3CL1 promoted cancer metastasis via the lymphatic pathway by stimulating lymphangiogenesis and transendothelial migration of lymph-circulating tumor cells." (PMID 38775151, 2024). "CX3CL1 increase in MOC1 tumors resulted in smaller tumor size with increased tumor keratinization." (PMID 38775151, 2024).
tumor (continued). "Using orthotopic syngeneic cancer cell lines in naturally occurring tumor immune microenvironments, we could observe the full capacity of chemokine CX3CL1 in cancer cells, immune cells, and tumor-supporting structures in the TME." (PMID 38775151, 2024). "This suggests that cancer cells with high CX3CL1 expression (CX3CL1hi) could induce immature tumor lymphangiogenesis in the TME." (PMID 38775151, 2024). "Although we expected the expression of CX3CL1 in metastatic LN (M) to be higher than the primary tumor (P), some cases showed similar expression or lower expression in metastatic LN compared to the primary tumor (M ≤ P)." (PMID 38775151, 2024). "CX3CR1+ T-cell subsets can be identified in tumors; however, it remains unclear whether they migrate from secondary lymphoid organs via the CX3CR1/CX3CL1 axis or directly differentiate from CX3CR1− CD8+ T cells in the tumor microenvironment." (PMID 38881188, 2024). "To further investigate the in vivo effects of CX3CL1 on cancer, we analyzed various areas that could predict cancer outcomes, including tumor size, keratinization, and metastasis." (PMID 38775151, 2024). "However, in a mouse model of breast cancer, IL-15Rα+TAM releases IL-15Rc (the IL-15/IL-15Rα complex) to reduce the expression of chemokine CX3CL1 in tumor cells, thereby reducing recruitment to CD8+T cells." (PMID 38279145, 2024). "Notably, our study does not negate the ability of CX3CR1+ CD8+ T cells to traffic to the tumor microenvironment if tumors secrete CX3CL1." (PMID 38881188, 2024). "However, if the receptor is present on tumor cells, CX3CL1 has been described to exhibit pro-tumorigenic and pro-metastatic properties." (PMID 38742103, 2024). "However, overexpression of CX3CL1 can partially reverse the promoting effect of LPS on tumor proliferation." (PMID 38915444, 2024). "In addition, CX3CL1 has antitumor effects by recruiting anti-tumor immune cells into the tumor microenvironment to control tumor growth." (PMID 38327747, 2024). "Together, these findings demonstrate the importance of tumor-specific genetic alterations as a mechanism for reprogramming the immune landscape in cancer and highlight p-VHL loss–mediated CX3CL1 upregulation as a specific driver of myeloid inflammation in ccRCC." (PMID 38618956, 2024). "Although CX3CR1+ CD8+ T cells are present in tumors, it remains unclear whether they directly differentiate from the CX3CR1− subset within the tumor microenvironment or are trafficked from secondary lymphoid organs via the CX3CL1/CX3CR1 chemokine axis." (PMID 38881188, 2024). "Moreover, a murine tumour prophylactic vaccination model was employed to analyse the effect of CX3CL1 on the activation of an adaptive immune response against MCA205 cells undergoing ICD." (PMID 39011040, 2024). "CCL5, CXCL9, CXCL10, CXCL11, and CX3CL1 are involved in the recruitment of CD8+ T cells to tumours." (PMID 38291183, 2024). "On PDTs, VACV GM-CSF+ could induce downregulation of other proteins involved in tumoral progression, such as CX3CL1 and CXCL12 chemokines." (PMID 38698850, 2024). "Additionally, CX3CL1 was found to significantly promote the migration of T24 cells, further supporting the role of CX3CL1 in tumor progression." (PMID 39409924, 2024). "ICAM‐1 mAb and siRNA result in a downregulation of CX3CL1‐induced tumour metastasis in OSCC cells." (PMID 37082943, 2023). "Finally, in view of the role of hypoxia and hypoxia inducible factor-1α (HIF-1α) in cell function, it was noted that this protein was required for IL-15R to suppress tumor cell CX3CL1 expression." (PMID 37296860, 2023). "The overexpression of CX3CL1 inhibited tumor growth and lung metastasis in vivo." (PMID 36794651, 2023). "It suggests the correlation between CX3CL1 and tumor prognosis." (PMID 37153002, 2023). "Interestingly, production of several cytokines that promote tumor immune resistance was upregulated when CT26 tumor cells were treated with CX3CL1." (PMID 37771579, 2023).
tumor (continued). "Moreover, CX3CL1 plays a role in tumor promotion and dissemination in patients with RCC besides CXCL12." (PMID 37021054, 2023). "Since CX3CL1 signaling through CX3CR1 leads to secretion of immunosuppressive mediators by the CT26 tumor, we hypothesized that CX3CR1 antibody could reduce the secretion of these mediators." (PMID 37771579, 2023). "Which indicates CX3CL1 plays an important role in tumor immune microenvironment." (PMID 37153002, 2023). "We next tested whether CX3CL1 will induce these soluble mediators in the presence of IFN-γ, and TNF-α since these inflammatory mediators are likely to be present in the tumor microenvironment and could potentially reduce CX3CL1 induced signals." (PMID 37771579, 2023). "It has been demonstrated that CX3CL1 has a tumor suppressing effect." (PMID 37153002, 2023). "I found CX3CL1 was differentially expressed in numerous cancer types, which indicated CX3CL1 may plays a potential role in tumor progression." (PMID 37153002, 2023). "Moreover, the cleavage products of ADAM10 and ADAM17, the C-X3-C motif chemokine ligand 1 (CX3CL1)/fractalkine, play a role in inflammation and angiogenesis within the tumor microenvironment." (PMID 37823051, 2023). "The activation of CX3CL1 (chemokine C-X3-C motif ligand 1, also known as fractalkine)/CX3CR1 (CX3C chemokine receptor 1) in tumor-associated microglia/macrophages (TAMs) increases the adhesion/migration capacity of GBM cells through the expression of MMP-2, -9, and -14." (PMID 37108208, 2023). "CX3CL1 corresponds with node metastasis and early tumour stage in OSCC patients." (PMID 37082943, 2023). "Several studies provide compelling evidence that MSCs can be genetically engineered to deliver anti-tumor drugs (PTX, DOX) and immunomodulatory factors (IL-12, IL-24, IFN-Υ, IFN-β, TRAIL, PEDF, apotin, CDA/UPRT and CX3CL1) to target cells, thereby conferring anti-tumor/anti-metastatic actions." (PMID 36739406, 2023). "Further research was conducted to evaluate the relationship between CX3CL1 and tumor stages." (PMID 37153002, 2023). "In this study, I first evaluated the expression levels of CX3CL1 in human cancer and normal tissues across various tumors and revealed the difference of CX3CL1 methylation level between normal and tumor tissues, which partially explained the differential expression of CX3CL1 in various cancers." (PMID 37153002, 2023). "However, the significant decrease in CX3CL1 after miR-200a-3p transfection in both pro-inflammatory and anti-inflammatory TMEs suggests the association of miR-200a with decreased immune effector cell infiltration and decreased tumor-suppressive activity, which may also result in higher metastasis." (PMID 37770496, 2023). "In addition, metalloproteinases MMP3, MMP9, MMP10 and MMP13, known to promote tumor growth, were upregulated by CX3CL1 mediated activation of CX3CR1." (PMID 37771579, 2023). "Studies have reported that CX3CL1 may exert anti-tumor effects in colorectal cancer and glioma via anticancer T cells and NK cells." (PMID 36397015, 2022). "The migration of tumor cells was reduced in CX3CL1 inhibitor group." (PMID 35478937, 2022). "Thus, we reason that CX3CL1 overexpression can improve ccRCC prognosis by inducing ferroptosis-mediated tumor-cell death." (PMID 36397015, 2022). "Additionally, to verify the relationship between T cell infiltration and CX3CL1 expression, we divided tumor tissues into high T cell infiltration and low T cell infiltration." (PMID 35530333, 2022). "In addition, immunofluorescence staining using xenograft ccRCC tumor tissues showed increased localization of CX3CL1; GPX4 and PCNA were found to have decreased expression in the OE-CX3CL1 group compared to that in the control group." (PMID 36397015, 2022). "Furthermore, the CX3CL1 expression level was closely related to the infiltration level of CD8+ T cells into the tumor microenvironment (TME)." (PMID 36397015, 2022).
tumor (continued). "Co-staining confirmed that CX3CL1 strongly expressed tumor tissues had more T cell infiltration." (PMID 35530333, 2022). "The migration of tumor cells was reduced in CX3CL1 blocking group." (PMID 35478937, 2022). "Importantly, we found that increased CX3CL1 expression level resulted in further recruitment of PDAC tumor cells." (PMID 35478937, 2022). "In tumor tissues, the higher the expression of CX3CL1, the higher the number of T cells, whether it is CD8+ T cells or CD4+ T cells." (PMID 35530333, 2022). "Finally, CX3CL1 overexpression inhibited tumor cell proliferation and metastasis and promoted tumor ferroptosis sensitivity in ccRCC." (PMID 36397015, 2022). "The result of Weston blot showed that CX3CL1 was more abundant in para-tumor samples." (PMID 35530333, 2022). "Moreover, to verify the recruitment of CX3CL1 to the CX3CR1-expressing tumor cells in PDAC liver metastasis of PDAC, we performed the transwell experiments by using in vitro recombinant protein." (PMID 35478937, 2022). "This study revealed the role of CX3CL1 as a tumor suppressor in ccRCC." (PMID 36397015, 2022). "Nevertheless, there is still controversy over the role of CX3CL1 in tumor-directed TAM migration." (PMID 35269652, 2022). "The decrease of CX3CL1 expression in tumor cells is related to the chemical modification of its DNA by methylation; this mechanism is known as epigenetic silencing and may result from evolutionary pressure on the cellular genome." (PMID 36397015, 2022). "Moreover, CX3CL1 expression was differentially correlated with various tumor histologies and stages." (PMID 36397015, 2022). "CX3CL1 expression was increased in tumor tissues in KIRC and KIRP, predicting better OS." (PMID 36059952, 2022). "Moreover, the relationship of CX3CL1 expression with the tumor microenvironment, especially the tumor immune microenvironment, was analyzed." (PMID 36397015, 2022). "Hence, the overexpression of CX3CL1 in tumor cells was shown to inhibit hepatocellular and colon tumor incidence in association with CD4 and CD8 T-cell infiltration in the tumors." (PMID 36429101, 2022). "In addition, it was showed that chemokine CX3CL1 interacts with its receptor CX3CR1 to induce TAM recruitment into tumor tissues and promote skin cancer progression." (PMID 34178692, 2021). "In the solid tumor, we observed slightly enhanced tumor growth in CX3CL1 overexpressing tumors." (PMID 34070094, 2021). "It has been reported that miR-125b is downregulated in TGCT and that low levels are associated to increased production of tumor-derived chemokine CSF1 and CX3CL1, which are known to control the recruitment of macrophages to the neoplastic sites that in turn stimulate tumor growth." (PMID 34440480, 2021). "Moreover, the application of shedding inhibitors to CX3CL1 overexpression tumors resulted in a slightly enhanced tumor growth." (PMID 34070094, 2021). "The effects of CX3CL1 were also verified by the subcutaneous tumour formation in nude mice, which showed that it could promote proliferation and invasion of A549 in vivo." (PMID 33191645, 2021). "Enrichment analysis and functional study based on expression array data suggested that the regulation of tumor growth by CX3CL1 might due to the enhance of the ERK/MAPK signaling pathway." (PMID 34671562, 2021). "CX3CL1 is a multifunctional chemokine, which is involved in a variety of tumor-relevant processes, such as immune cell attraction and enhanced tumor–immune cell interaction on the one hand, and in enhancing tumor cell proliferation, invasion, angiogenesis and increased metastasis on the other hand." (PMID 34070094, 2021). "Therefore, during the ~7-week treatment study, a high concentration of CX3CL1 in the tumor of MDA-MB-453CX3CL1 HTM was warranted." (PMID 34070094, 2021).